UBE2S (ubiquitin conjugating enzyme E2 S)
Diseases named in the same sentence as UBE2S in open-access papers (continued):
Sharing a sentence is not in itself a finding about the gene and the disease.
tumor (continued). "The result of our study demonstrated that UBE2S was negatively correlated with the immune score and stromal score, indicating that a higher UBE2S expression with a lower level of tumor-infiltrating immune and stromal cells may be an indicator of an advanced stage and unsatisfied prognosis." (PMID 35578600, 2022). "In addition to contribution to tumor proliferation, UBE2S plays important roles in DNA repair." (PMID 34123793, 2021). "Our findings reveal tumor-intrinsic mechanisms suppressing NK cell activity in NSCLC, proposing XBP1s, IL-6, and UBE2S as actionable targets to enhance NK-based immunotherapies." (PMID 41254082, 2025). "We found the increased expression of PFKP, TPX2, UBE2S, ST6GALNAC4, ADAM15, G6PD, and KPNA2, but decreased expression of GOT2 in tumor samples compared to normal samples." (PMID 40307857, 2025). "The expression of UBE2S, HMMR and KRT6A expression in tumor tissues was substantially higher than that in adjacent non-cancerous tissues." (PMID 37199651, 2023). "As in tumors, previous studies had showed that UBE2S is overexpressed in renal, breast, oesophageal, cervical, HCC, and brain glioma cancer, which was related to tumor and tissue specificity." (PMID 37563971, 2023). "Studies have found that UBE2S can specifically ubiquitinate and degrade VHL via the 26S proteasome to stabilize hypoxia‐inducible factor (HIF) and eventually promote tumor progression." (PMID 37563971, 2023). "It was found that the expression level of KCTD12, SIAH1, TRIM58, UBE2S, and UBE2T were significantly decreased in tumor tissue compared with the normal tissue, but TRIM47 was upregulated." (PMID 36534449, 2022). "Intriguingly, we noticed the activity of the ubiquitin-mediated proteolysis pathway, as well as the expression of multiple ubiquitin-conjugating enzymes including UBE2S, UBE2E3 and UBE2C, were upregulated in tumor cells from solid samples." (PMID 36138435, 2022). "Particularly, nuclear UBE2S content was observed in 41 of 80 (51.25%) primary HCC tissues, compared with 17 of 80 (21.25%) adjacent non-tumor tissues (P < 0.01)." (PMID 33589597, 2021). "Functional assays revealed that overexpression of UBE2S promoted the proliferation, invasion, metastasis, and G1/S phase transition of HCC cells in vitro, and promoted the tumor growth significantly in vivo." (PMID 33589597, 2021). "To explore the role of UBE2S in HCC, we analyzed its mRNA expression in HCC and adjacent non-tumor tissues using the TCGA database, GSE14520 and GSE17856 data sets." (PMID 33589597, 2021). "Src/FAK/p-cortactin, Akt/mTOR/c-Myc, UBE2S/hypoxia, and reactive oxygen species (ROS) signaling activated and promoted the metastasis of A431-III tumor cells." (PMID 31731716, 2019). "The expression of UBE2S in HIN and LIN was situated in the cytoplasm and nucleus, and the expression of HIF‐1α and FOXM1 in HIN and LIN was primarily situated in the nucleus of tumor cells." (PMID 41427004, 2025). "Notably, in HIN and LIN, the coefficient correlation of UBE2S, HIF‐1α, and FOXM1 increased as an increase in tumor grade." (PMID 41427004, 2025). "We found that KO in the lung of Ube2c, but not Ube2s, substantially reduced the tumor burden and prolonged mouse lifespan, indicating that Ube2c is a Kras-cooperative gene, largely required for Kras-induced lung tumorigenesis." (PMID 36548081, 2023). "Taken together, UBE2S may play a vital role in the TME and could confer tumor immune escape, although further investigation is needed to validate these conclusions." (PMID 35578600, 2022). "Furthermore, there is a paucity of knowledge regarding the distinct mechanisms of action exhibited by UBE2S in different tumor types, and a lack of exploration into the mechanisms underlying its drug resistance." (PMID 38312603, 2024). "However, there was no obvious distinction in the weights of mice from the UBE2S‐shRNA and control‐shRNA groups in subcutaneous xenograft tumor models." (PMID 37563971, 2023).
tumor (continued). "Furthermore, UBE2S was demonstrated to be negatively correlated with the von Hippel-Lindau tumor-suppressor (pVHL), which mediated the ubiquitin-dependent proteolysis of HIF1A, in multiple tumor cell lines." (PMID 36138435, 2022). "In addition to a higher expression level of UBE2S in HCC than the corresponding normal tissues, we confirmed that the transcript level of UBE2S was obviously higher in HCC with aggressive phenotypes, including large tumor size, recurrence, and advanced TNM stage." (PMID 34785642, 2021). "In addition, they found that the ubiquitin conjugating enzyme E2 S (UBE2S, formerly E2-EPF) was a significant predictor of tumor burden, whereas ISG15 was not." (PMID 27626310, 2016). "FatiGO+ analysis showed that tumor libraries had significantly more expressed genes related to "cell organization and biogenesis" (GO:0016043), KRT7, PDIA3, PPGB and TRAPPC5 (p = 0.005); and "ligase activity" (GO:0016874), UBE2S and MTHFD1 (p = 0.028) than normal libraries." (PMID 18302799, 2008). "Importantly, the differential expression of UBE2S and UBE2C across histologic subtypes were further corroborated in bulk transcriptome from the TCGA and the East Asian ancestry (EAS) cohorts, as well as proteome from the Clinical Proteomic Tumor Analysis Consortium (CPTAC) cohort." (PMID 36138435, 2022). "However, no convincing conclusion has been drawn on whether and how UBE2S promotes TME remodeling to favor tumor malignant phenotypes and immunotherapeutic resistance." (PMID 35578600, 2022). "UBE2S, HMMR, TMPRSS11E and KRT6A were found to be up-regulated in tumor tissues relative to surrounding non-cancerous and normal tissues in the screening cohort." (PMID 37199651, 2023).
adenocarcinoma (3 papers, 2020 to 2024). A common cancer characterized by the presence of malignant glandular cells. "Manipulation of UBE2S gene expression through knockdown or overexpression in adenocarcinoma cells resulted in increased nuclear translocation of p65 and heightened NF-κB activity." (PMID 38312603, 2024). "The mechanism underlying the action of UBE2S involves its direct interaction with IκBα in LUAD to stimulate the NFκB pathway, which in turn activates the EMT signal to promote adenocarcinoma metastasis." (PMID 37199651, 2023).
infection (2 papers, 2013 to 2022). The state of being infected such as from the introduction of a foreign agent such as serum, vaccine, antigenic substance or organism. "The downregulation of ube2s expression may increase IFN production and improves host immunity against infection." (PMID 35927758, 2022).
UBE2S also shares sentences with these, for which no sentence is quoted: lung squamous cell carcinoma (2 papers); adenoid cystic carcinoma (1); clear cell renal cell carcinoma (1); colon cancer (1); esophageal carcinoma (1); influenza (1); leukemia (1); meningioma (1); metastatic tumors (1); myocardial infarct (1); rectal adenocarcinoma (1); Sepsis (1); serous ovarian cancer (1); testicular germ cell tumor (1); triple-negative breast carcinoma (1); viral hepatitis (1).